INS (insulin)
Diseases named in the same sentence as INS in open-access papers (continued):
Sharing a sentence is not in itself a finding about the gene and the disease.
diabetes (continued). "We conclude that age-related epigenetic alterations in blood partially reflect DNA methylation changes in human pancreatic islets and associate with increased insulin secretion in vivo, as well as lower diabetes risk." (PMID 27029739, 2016). "Diabetes arises from irreversible damage of the β-cells of the islets in the pancreas, causing a reduction or deregulation of insulin." (PMID 27257845, 2016). "Insulin use both in the crude analysis and after adjustment for BMI, diabetes duration and metabolic control was associated with significantly elevated risk of cancer occurrence." (PMID 27724912, 2016). "It was also found that metformin prevented partially insulin-deficient diabetes-induced bone microarchitecture alterations, and enhance the process of bone repair in diabetic and nondiabetic rats." (PMID 27316923, 2016). "Diabetes is a long-term condition characterized by hyperglycaemia in the presence of defects of insulin secretion or insulin action, or both, and is a major cause of morbidity and premature mortality globally." (PMID 27561822, 2016). "Despite the abundant research regarding the use of insulin in diabetes, the long-term application of insulin is associated with devastating side effects." (PMID 27212152, 2016). "Leptin-deficient ob/ob mice are overweight, insulin-resistant, and develop type 2 diabetes mellitus over time due to deficiency of the appetite regulating hormone leptin, which has immunomodulatory properties." (PMID 27486384, 2016). "Insulin decreases blood glucose levels and insufficient insulin release from the β-cells causes most forms of diabetes mellitus." (PMID 27539300, 2016). "The increasing risk of cancer incidence with duration of diabetes can be explained by cumulative effect of hyperglycemia, use of insulin, and weight gain developing in the course of the disease." (PMID 27724912, 2016). "Since a pathogenic function of autoreactive B cells in diabetes can be presentation of self Ag, we measured the capacity of these immature TR-B cells to present Ag to a T cell clone specific for insulin." (PMID 27834793, 2016). "Hyperglycemia, hyperlipidemia and impaired insulin signaling during the development of diabetes can cause diabetic complications, such as diabetic neuropathy, resulting in significant morbidity and mortality." (PMID 27483315, 2016). "Taking this risk and that of heart failure in diabetes mellitus into account, the best risk–benefit ratio exists for metformin and insulin." (PMID 26772807, 2016). "Multiple-low-dose STZ-induced diabetes was associated with diminished insulin-positive beta cells (p < 0.001), augmented glucagon-positive alpha cells (p < 0.001) and decreased GPR119 expression (p < 0.001)." (PMID 27677765, 2016). "The Pro12Ala mutation of PPARγ2 is a risk factor of weight gains in human obese patients; in contrast, the Ala12 allele improves insulin sensitivity and has protective effect against obesity and type 2 diabetes mellitus in lean patients." (PMID 27483259, 2016). "Diabetes, a complex metabolic disorder caused by insulin insufficiency and/or insulin dysfunction, is characterized by abnormal blood glucose and insulin levels." (PMID 27483315, 2016). "Diabetes mellitus (DM) is a chronic metabolic disorder manifested by a loss of pancreatic islet B cell, decreased serum insulin, and hyperglycemia." (PMID 27027354, 2016). "Beliefs and perceptions about insulin have been associated with adherence to treatment and diabetes control." (PMID 26682231, 2016). "Type-2 Diabetes (T2D) is a disease that results when the body either doesn’t make enough insulin or cannot use its own insulin properly (The American Diabetes Association [ADA], 2015)." (PMID 27157156, 2016). "The accumulated evidence shown by the literature makes it possible to establish that insulin-dependent blood flow increments are blunted in obese, and type 2 diabetes mellitus (T2DM) patients, conditions associated with insulin resistance." (PMID 27014078, 2016).
diabetes (continued). "Diabetes Mellitus (DM) is a chronic metabolic disease characterized by deficiency in insulin production or resistance to its action, resulting in hyperglycemia and metabolic alterations." (PMID 27383710, 2016). "It is characterized by hyperglycemia occurring as a result of impaired insulin secretion, insulin resistance and increased glucose output by liver or a combination of them." (PMID 28330327, 2016). "Diabetes is a cluster of metabolic syndrome featured by the deficiency of insulin secretion, insulin action or both, which causing metabolic disorders of nutrient substance including carbohydrate, protein, fat, water and electrolyte." (PMID 27457614, 2016). "In this analysis GA was important in all groups with regard to a significant association with diabetes, adiponectin was important in Fukuoka women and Framingham men, and insulin was important in Fukuoka men." (PMID 27830830, 2016). "Obesity is frequently associated with diabetes mellitus, a group of metabolic diseases characterised by hyperglycaemia resulting from defects in insulin secretion, insulin action, or both." (PMID 26901760, 2016). "Despite the recognized pathological role of MG in diabetes and diabetic complications, little previous study has, to our knowledge, investigated the possible impact of MG on insulin secretion or the mechanism underlying any such effect." (PMID 26779540, 2016). "In newborn animals, the damage extends to hampered insulin production, predisposing to diabetes in later life, impaired bone development, lung injury leading to bronchopulmonary dysplasia (BPD) and cerebellar injuries." (PMID 27304988, 2016). "The deficiency of insulin can lead to diabetes mellitus or hyperglycemia which is related to high blood sugar levels in the human body." (PMID 26784202, 2016). "Glibenclamide (glyburide) is widely used in the treatment of several forms of diabetes, because it binds to the sulphonylurea receptors, which associate with the ATP-sensitive K+ channels of beta cells, thus stimulating insulin release." (PMID 28006000, 2016). "From the clinical point of view, upregulated FOXO-1 raises a state of insulin resistance and diabetes, due to a loss of insulin sensitivity, and the consequent hyperglycemia or high glucose accelerates cellular damage." (PMID 26839893, 2016). "Despite the good agreement with estimates for α included, there were some NDM exceptions where altered ATP inhibition was insufficient to generate a full suppression of [Ca2+] and insulin that would cause diabetes." (PMID 27681078, 2016). "There are two main types of diabetes: type 1 (insulin-dependent), with β-cell destruction and insulin deficiency, and type 2, with progressive defect of insulin secretion on the background of insulin resistance." (PMID 26950142, 2016). "Since the reduced insulin secretory capacity is a risk of the onset of diabetes in Asian, reduction of serum TC is expected to ameliorate a risk of diabetes." (PMID 26881755, 2016). "Diabetes mellitus (DM) is a clinical syndrome caused by a disorder in insulin secretion and/or action which results in metabolic changes, especially high blood glucose." (PMID 27876085, 2016). "Expression of Insr in the rodent lung was verified some time ago, at both fetal and adult stages, and alterations in insulin signaling, including diabetes and metabolic syndrome have been associated with an increased risk in lung diseases." (PMID 27861515, 2016). "Premorbid intelligence is associated with diabetes precursors – obesity and high insulin – and diabetes itself, but cognitive impairment is related to diabetes only." (PMID 27642517, 2016). "In contrast, mice overexpressing miR-7a-2 in β-cells developed pronounced diabetes from 4 weeks of age and this was associated with a decrease in circulating insulin levels due to a secretory deficit of β-cells." (PMID 28123396, 2016).
diabetes (continued). "T2DM is characterized by decreased insulin sensitivity in peripheral tissues and resulting perturbation of insulin secretion [American Diabetes Association (ADA) 2014]." (PMID 27128844, 2016). "Low levels of insulin or IGF-1 and elevated levels of glucocorticoids induce the loss of muscle protein in diabetes, and insulin resistance is a characteristic feature of many systemic diseases with muscle wasting." (PMID 26856534, 2016). "In mice, β-cell-selective disruption of pdx-1 led to the development of diabetes with increasing age and was associated with reduced insulin and GLUT-2 (a glucose-sensing and -transporting molecule located on the surface of β-cells) expression." (PMID 25695047, 2015). "Although some of the participants who received transplants were on basal-bolus insulin regimens, insulin pump therapy was associated with being listed for islet transplantation, perhaps reflecting a staged approach to diabetes management in many patients." (PMID 25810037, 2015). "An insulin-deficient model of diabetes enables evaluation of the effects of the DPP4inh independent of glycemic control as DPP4inh will not have a significant hypoglycemic effect due to the lack of a significant insulin response mediated by GLP-1." (PMID 26379674, 2015). "In rodents, the most common experimental model of short-term insulin-deficient diabetes is the elimination of pancreatic β islet cells by administration of STZ." (PMID 26652274, 2015). "Excessive hepatic lipogenesis is a hallmark feature of many models of obesity and diabetes, although the causal relationship between tissue lipid accumulation and insulin resistance is unclear." (PMID 25922847, 2015). "Together, these studies in STZ-induced diabetes suggest an improvement of peripheral insulin sensitivity and/or more active insulin in Mif-deficient mice." (PMID 26124760, 2015). "These included chronic diseases and the need to take medications that caused weight gain, such as insulin for diabetes or steroids for asthma or arthritis." (PMID 26855786, 2015). "People with insulin-treated diabetes had a modestly increased risk of RTAs compared with the population as a whole, with an odds ratio of 1.4 (1.2–1.6)." (PMID 28702227, 2015). "One of the key impacts was the advocating use of insulin and statin for the better control of diabetes mellitus and the associated hyperlipidemia at the primary care level." (PMID 26388950, 2015). "Very few studies have evaluated the association of LTL with obesity/diabetes-related biomarkers such as leptin, adiponectin, or insulin, glucose or HOMA scores." (PMID 26380096, 2015). "The polymorphism of calpain-10 has been linked and associated with diabetes susceptibility, glucose homeostasis, insulin secretion and insulin activation." (PMID 26120352, 2015). "Diabetes mellitus is characterized by chronic hyperglycemia due to insulin resistance and defect in insulin secretion and/or insulin action caused by Langerhans islets’ β-cell failure." (PMID 26157708, 2015). "Insulin resistance (IR) is a reduction in reaction or sensitivity to insulin and is considered to be the common cause of impaired glucose tolerance, diabetes, obesity, dyslipidemia, and hypertensive diseases." (PMID 25887236, 2015). "It is well established that the loss of insulin immunostaining seen in many mouse models of diabetes is paralleled by an increase in glucagon immunostaining." (PMID 25982967, 2015). "A hallmark of both types I and II diabetes is the progressive β-cell insufficiency in the pancreas, which results in defects in insulin secretion and hyperglycemia." (PMID 26074958, 2015). "Diabetes is characterized by hyperglycemia due to an absolute or relatively deficient insulin levels." (PMID 26490765, 2015). "This disrupts the balance between insulin and glucose cycles, causing reductions in insulin sensitivity and increases in glucose concentration, a prelude to diabetes." (PMID 25988133, 2015).
diabetes (continued). "Some prospective data have shown that diabetes mellitus is a statistical risk factor for osteoporosis, especially in cases of insulin-treated diabetes, a long history of diabetes, or in the elderly." (PMID 25945273, 2015). "Poor cognitive performance in diabetes has been associated with increase in insulin resistance and decline in cerebrospinal fluid (CSF) insulin level." (PMID 26161865, 2015). "The conversion of non-β cells into insulin-producing cells in vivo is an innovative approach to treat diabetes and circumvents the need for immunosuppression associated with allogeneic transplantation." (PMID 26690959, 2015). "Diabetes comprises a complex of metabolic disorders associated with impaired insulin secretion and glucose metabolism." (PMID 25609196, 2015). "Recently, accumulating evidence has cast a spotlight on type 2 diabetes mellitus as a potent risk factor for AD development, which is likely to be mediated by insulin and insulin-like growth factors (IGF-1, IGF-2)." (PMID 26556341, 2015). "Pancreatic beta cells regulate metabolic homeostasis by controlled secretion of insulin; impaired beta cell function leads to persistently elevated levels of blood glucose, the hallmark of diabetes." (PMID 25706282, 2015). "The strength of this paper was the first in evaluate the relationship of thyroid function and insulin resistance with a dynamic test in euthyroid adolescents with diabetes risk factors, the weakness is the cross sectional design." (PMID 25780389, 2015). "Hyperglycaemia is the hallmark for diabetes and results both from insufficient insulin production in pancreatic β cells, as in T1D, and from the increase of systemic insulin resistance, as in T2D." (PMID 26171112, 2015). "Patients with progression of kidney disease are at increased risk of hypoglycemia due to decreased clearance of insulin and some medications used to treat diabetes as well as impairment of renal gluconeogenesis from lower kidney mass." (PMID 28702221, 2015). "Considering that increases in levels of circulating sugar is a hallmark of diabetes, the insulin response was evaluated in the FB of larvae expressing a tGPH reporter." (PMID 25692475, 2015). "Inappropriate insulin sensitivity underlies diseases from diabetes to polycystic ovary syndrome and cancer." (PMID 26202599, 2015). "In animal experiments, females showed greater susceptibility towards developing diabetes because of lower insulin secretion and higher blood glucose levels as compared to male diabetic rats upon exposure to STZ." (PMID 25726699, 2015). "Type 2 diabetes mellitus is predominantly caused by abnormal sugar and lipid metabolism, due to the relative deficiency of insulin (insufficient insulin secretion and insulin resistance), or excessive glucagon levels." (PMID 25574213, 2015). "In analogy to diabetes mellitus, increased insulin resistance and diminished insulin secretion are the underlying causes of PTDM, however the latter seems to be the predominant factor." (PMID 26398489, 2015). "Particularly female gender, pubertal diabetes onset, intensive insulin therapy, and higher insulin dose were identified as risk factors for body weight gain." (PMID 26125029, 2015). "Santé Diabète was able to supply essential diabetes medicines and insulin to the north of the country by using diabetes patient associations, health professionals and humanitarian NGOs active in the north of the country." (PMID 25937831, 2015). "There are two main types of diabetes mellitus: diabetes mellitus type I, which is also called insulin-dependent and is caused by impairment of insulin secretion from pancreatic cells." (PMID 25949955, 2015). "Indians as a group are one of the most insulin-resistant populations in the world and it is thought that this contributes to their high risk of diabetes and CVD." (PMID 25940643, 2015).
diabetes (continued). "High copeptin levels are associated with significantly higher risk of diabetes in older men which is to some extent mediated through its effect on insulin and related metabolic pathways." (PMID 26158609, 2015). "Free radicals induced oxidative damage of pancreatic β-cells has been implicated in impaired insulin production/function, a major risk factor of diabetes development." (PMID 26788368, 2015). "Progressive beta-cell dysfunction and cell death, with impaired glucose-stimulated insulin secretion response and resulting hyperglycemia, is the hallmark and primary cause of diabetes and chronic related complications observed in HNF1α-MODY patients." (PMID 27551471, 2015). "Branched chain and aromatic AAs have been associated with insulin-resistant states, including diabetes, in many other studies in populations of mostly European origin." (PMID 25693751, 2015). "This balance is disturbed in patients with diabetes, resulting in loss of first phase insulin response and increased glucagon levels." (PMID 26064864, 2015). "Diabetes mellitus is one of the most severe endocrine metabolic disorders associated with the absence or decreased level of insulin hormone or its reduced action on cells." (PMID 25905778, 2015). "Our observation of the opposite effects of simvastatin and pravastatin on glucose-stimulated insulin secretion is in agreement with previous reports showing that simvastatin, but not pravastatin, was associated with increased risk of incident diabetes." (PMID 26561346, 2015). "While hyperglycemia is a major factor, diabetes is associated with changes in insulin, IGF-1 and many other hormones and metabolites, including free fatty acid, amino acids, advanced glycation end products, and components of the oxidative stress pathway." (PMID 26075045, 2015). "Diabetes is a complex metabolic disorder characterized by a relative or absolute deficiency in insulin secretion and/or its influence." (PMID 26528968, 2015). "Diabetes mellitus (DM) is a chronic disease, which is characterized by hyperglycemia that results from absolute or relative deficiency of insulin." (PMID 26151207, 2015). "Obesity-associated chronic low-grade inflammation is responsible for the decrease of insulin sensitivity, which makes obesity a major risk factor for insulin resistance and related diseases such as type 2 diabetes mellitus and metabolic syndromes." (PMID 26136779, 2015). "The insulin/IGF axis is deeply involved in diabetes-associated increased risk and progression of cancer, to such an extent that it has been demonstrated that cancer cells overexpress both insulin and IGF-1 receptors." (PMID 26171112, 2015). "This present report is the first to describe the pattern of multiple diabetes-associated autoantibodies in non-insulin-requiring adult-onset diabetes in a Chinese population." (PMID 26239144, 2015). "Prior studies have suggested that carriers of the 12 Ala allele show significantly improved insulin sensitivity and protection from diabetes as compared with wild type Pro/Pro homozygotes." (PMID 25889595, 2015). "The levels of insulin, insulin-like growth factor, obesity and diabetes are considered to be independent risk factors for the development of BPH." (PMID 25809513, 2015). "Age, diabetes duration, being overweight and being under insulin treatment were independently associated with diabetic retinopathy." (PMID 25925666, 2015). "In diabetes, which is established as a strong independent cardiovascular risk factor, insulin-dependent signaling in ECs is down-regulated due to insulin resistance." (PMID 26696899, 2015). "In the control group, many high-risk subgroups (for example, male sex, diabetes, hypertension, high sagittal diameter, high insulin, high glucose, high urine albumin excretion) had a higher incidence of albuminuria than the corresponding low-risk subgroups." (PMID 24798033, 2015).